KCTD4 (potassium channel tetramerization domain containing 4)
Synonyms: bA321C24.3
Tractability: PROTAC: its protein half-life has been measured.
Gene: Protein-coding gene on chromosome 13 (45,192,853 to 45,201,045, reverse strand). Ensembl gene ENSG00000180332.
Subcellular location (Human Protein Atlas): Centriolar satellite
Gene Ontology:
Molecular function: protein binding; identical protein binding
Biological process: protein homooligomerization
Genetic constraint (gnomAD): Loss-of-function variants: 12 observed, 19.17 expected, observed/expected ratio (o/e) 0.63, 90% interval 0.4 to 1.01. The upper end of that interval is the gene's LOEUF score, 1.01, which puts it in group 4 of 6, group 1 being the genes least tolerant of losing a copy. Missense variants: 250 observed, 319.64 expected, observed/expected ratio (o/e) 0.78, 90% interval 0.7 to 0.87. Synonymous variants: 124 observed, 116.57 expected, observed/expected ratio (o/e) 1.06, 90% interval 0.92 to 1.24.
Homologues: Orthologues: chimpanzee KCTD4 (100% identical), macaque KCTD4 (100% identical), pig KCTD4 (99% identical), dog KCTD4 (99% identical), rabbit KCTD4 (98% identical), guinea pig KCTD4 (97% identical), mouse Kctd4 (97% identical), rat Kctd4 (96% identical), tropical clawed frog kctd4 (82% identical), zebrafish kctd4 (56% identical), Drosophila melanogaster twz (19% identical), Caenorhabditis elegans F32B4.5 (12% identical). Paralogues in human: KCTD21 (26% identical), KCTD11 (26% identical), KCTD6 (24% identical), KCTD15 (21% identical), KCTD1 (20% identical), KCTD8 (20% identical), KCTD19 (19% identical), KCNRG (18% identical), KCTD16 (18% identical), KCTD12 (17% identical), KCTD7 (17% identical), KCTD18 (16% identical), and 1 more.
Diseases named in the same sentence as KCTD4 in open-access papers:
KCTD4 is named in the same sentence as 8 diseases in open-access papers, as found by Europe PMC text mining. Sharing a sentence is not in itself a finding about the gene and the disease. The quoted sentences say what the papers report.
prostate carcinoma (1 paper, 2022). A carcinoma that arises from epithelial cells of the prostate gland. "As results, high KCTD4 expression, low THBS2 expression, and high ACPP expression were associated with favorable BCRFS of prostate cancer patients; and high expression levels of HOPX, TMEM132A, and ZNF467 were associated with shorter MFS of prostate cancer patients." (PMID 36195908, 2022).
Sepsis (1 paper, 2023). Sepsis is defined as life-threatening organ dysfunction caused by a dysregulated host response to infection. "Using SHAM expression levels as another control variable, we further identified six genes (Fxyd4, Apex2l1, Kctd4, 7SK, SNORD94, and SNORA53) that were highly expressed after sepsis induction and observed that their expression levels were attenuated by mitochondrial transplantation." (PMID 37895006, 2023).
cancer (1 paper, 2022). A tumor composed of atypical neoplastic, often pleomorphic cells that invade other tissues. "In addition, 1 SNP was detected in KMT2C, a BC oncogene, and 9 others were detected in or near 10 genes (SERAC1, DAGLB, MACF1, NVL, FBXW4, FANK1, KCTD4, CAVIN1; ATP6V0A1 and ZBTB20-AS1) previously associated with non-BC cancers." (PMID 35589867, 2022).
tumor (1 paper, 2022). "The deregulation of both FANK1 and KCTD4 may be a consequence of the observed somatic variants, thus suggesting another association with tumor development and their use as an early detection biomarker in a cfDNA-based assay." (PMID 35589867, 2022).
KCTD4 also shares sentences with these, for which no sentence is quoted: autism (1 paper); leukemia (1); lymphoma (1); schizophrenia (1).